OGG1 (8-oxoguanine DNA glycosylase)
Diseases named in the same sentence as OGG1 in open-access papers (continued):
Sharing a sentence is not in itself a finding about the gene and the disease.
Obesity (continued). "Conversely, enhanced expression of the human OGG1 gene renders mice resistant to obesity and adiposity." (PMID 34604220, 2021). "Conversely, transgenic animals with mitochondrially-targeted overexpression of OGG1 (Ogg1Tg) are resistant to age- and diet-induced obesity." (PMID 33503804, 2021). "We have previously reported that HFD-fed Ogg1-/- mice are prone to diet-induced obesity and adiposity, relative to WT controls." (PMID 31935236, 2020). "Conversely, we have shown that overexpression of a mitochondrially-targeted OGG1 results in significant protection from diet-induced obesity, indicating an important role for OGG1 activity in regulating cellular metabolic homeostasis." (PMID 31935236, 2020). "Taken together, these data indicate that in addition to their proclivity to obesity and metabolic disease, Ogg1-/- mice are prone to colonic inflammation." (PMID 31935236, 2020). "Here, we demonstrate that transgenic targeting of OGG1 to mitochondria confers significant protection from diet-induced obesity, insulin resistance, and adipose tissue inflammation." (PMID 30291284, 2018). "Here we show that targeting OGG1 localization to mitochondria alone confers significant protection against diet-induced obesity and adiposity through specific metabolic adaptations in epididymal white adipose tissue (eWAT)." (PMID 30291284, 2018). "Similarly, cg05439191 is annotated to the TSS200 region of the OGG1 gene, whose expression is also affected by methylation and plays a significant role in obesity-related metabolic pathways." (PMID 40702573, 2025). "Targeting human OGG1 to mitochondria protected against HFD-induced obesity, insulin resistance, oxidative mitochondrial DNA damage in the liver and showed decreased expression of liver gluconeogenic genes in Ogg1-KO mice, suggesting a putative protective mechanism." (PMID 39596235, 2024). "Indeed, mt-hOGG1 expression significantly attenuated oxidative mtDNA damage in the liver and protected from obesity, hyperglycemia, and insulin resistance phenotype in HFD-fed Ogg1-KO mice." (PMID 39596235, 2024). "Previously, it has been shown that lack of OGG1 is associated with the development of obesity and metabolic syndrome." (PMID 39596235, 2024). "Therefore, OGG1 is a promising biomarker in obesity-related CRC and can act as a protective factor against CRC." (PMID 36982562, 2023). "As for obesity, Ogg1 in mice seems to play a protective role against obesity." (PMID 36982562, 2023). "Interestingly, our studies indicate an important function for OGG1 in protecting against genetically-induced obesity." (PMID 34604220, 2021). "Ogg1−/− mice are prone to diet-induced obesity and inflammation." (PMID 33503804, 2021). "Given our recent report of mitochondrial OGG1 being protective against obesity and metabolic disease, it will be interesting to determine if alterations in mtDNA integrity and mitochondrial function may be observed in carriers of the Ser326Cys mutation." (PMID 30700008, 2019). "Previous murine observations and our results point to a potential role of OGG1 in protecting and/or resistance against endogenous obesity- and cancer-related oxidative stress, suggesting that this DNA glycosylase may be a promising target for developing DNA glycosylase inhibitors." (PMID 36982562, 2023). "Therefore, we hypothesize that obesity could alter the expression and methylation profile of the OGG1 gene in VAT in the context of cancer, ultimately contributing to DNA damage and increasing the risk of CRC." (PMID 36982562, 2023). "Given our observations of increased propensity to diet-induced obesity and insulin resistance in Ogg1−/− mice, especially under conditions of increased oxidative stress, we were interested in determining the relative contribution of mitochondrial OGG1 to whole body energy homeostasis." (PMID 30291284, 2018).
Obesity (continued). "However, it is notable that in Ogg1-/- mice, these increases in markers of mitochondrial fission precede the development of obesity or insulin resistance, and may therefore be involved in the etiology of metabolic aberrations observed in these mice." (PMID 28727777, 2017). "Using Ogg1-KO/Tg mice, we showed that mitochondrial delivery of hOGG1 significantly lowers oxidative mtDNA damage and thus, obesity, hyperglycemia, and insulin resistance phenotype in HFD-fed Ogg1-KO mice." (PMID 39596235, 2024). "Also, a recent study showed that OGG1 plays a critical role in modulating mitochondrial energetics in WAT and whole-body energy balance, thus protecting against obesity in mt-hOGG1-overexpressing transgenic WT mice." (PMID 39596235, 2024). "Here, we hypothesize that 8-oxoguanine DNA glycosylase 1 (OGG1)—a DNA repair enzyme—may represent an attractive target that connects colorectal cancer (CRC) and obesity." (PMID 36982562, 2023). "Neither Nrf2 nor Keap1 was affected by maternal obesity or grape juice intake, and antioxidant genes Ogg1, Ogg2, Sod1 or Sod2 were not affected either." (PMID 32731460, 2020). "A recent study from our lab demonstrated that mitochondrial-targeting of OGG1 confers significant protection against diet-induced obesity and insulin resistance, even in the complete absence of nuclear OGG1." (PMID 30700008, 2019). "We have previously shown that mice lacking the BER enzyme OGG1 are prone to obesity and insulin resistance with increasing age or upon high-fat diet (HFD) feeding." (PMID 28727777, 2017). "Mice lacking the OGG1 gene product are prone to multiple features of the metabolic syndrome, including high-fat diet-induced obesity, hepatic steatosis, and insulin resistance." (PMID 28727777, 2017). "While numerous studies showed that lack of OGG1 in mice contributes to obesity and metabolic dysfunction, the precise tissue-specific mechanisms of insulin resistance in Ogg1-KO mice remain unknown." (PMID 39596235, 2024). "We have previously demonstrated that mice lacking endogenous OGG1 (Ogg1–/–) are prone to diet-induced obesity (DIO) and its sequelae, including insulin resistance, ectopic lipid accumulation in liver and skeletal muscle, gut dysbiosis, and chronic inflammation." (PMID 34604220, 2021). "Indeed, even in the absence of any endogenous OGG1, as in the Ogg1−/−;Tg animals, mitochondrially-targeted OGG1 significantly protects against development of obesity." (PMID 30291284, 2018). "In addition, the data provided in this review point to a novel mechanism—the potential role of OGG1–BER in the maintenance of chronic inflammation, not only in the lungs, but also in other systemic diseases—such as cardiovascular, arthritis, cancer, dementia, obesity, and diabetes." (PMID 25250913, 2014).
colorectal cancer (26 papers, 2006 to 2023). A primary or metastatic malignant neoplasm that affects the colon or rectum. "This study was designed to investigate the association between XRCC1 (rs25487) and OGG1 (rs1052133) polymorphisms and susceptibility to colorectal cancer (CRC) in the Ahvaz city, south-west Iran." (PMID 32711416, 2020). "In view of the role of the polymorphism in BER enzymes in colorectal carcinogenesis, we evaluated the influence of the APE1 Asp148Glu polymorphism on APE1, XRCC1, PARP1 and OGG1 expression in normal and tumor samples from patients with colorectal cancer." (PMID 25268610, 2014). "Therefore, this study was designed to investigate the association between the polymorphisms of DNA repair genes, including XRCC1 (rs25487) and OGG1 (rs1052133) given their susceptibility to colorectal cancer in the Ahvaz city, south-west Iran." (PMID 32711416, 2020). "Thus, we evaluated the influence of APE1 T2197G (Asp148Glu) polymorphism on APE1, XRCC1, PARP1 and OGG1 expression in normal and tumor samples from patients with colorectal cancer." (PMID 25268610, 2014). "Thus, taking into account the role of BER in colorectal carcinogenesis, the effects of the APE1 Asp148Glu polymorphism on APE1, XRCC1, PARP1 and OGG1 gene expression were evaluated in patients with colorectal cancer." (PMID 25268610, 2014). "Conversely, increased OGG1 protein expression and activity has been observed in colorectal cancer tissues." (PMID 33282879, 2020). "MUTYH and OGG1 tissue expression was quantified by RT-PCR in patients with colorectal cancer and the values were compared in normal and neoplastic tissues." (PMID 29257843, 2017). "This OGG1 SNP interacts synergistically with MUTYH SNP rs3219489, encoding p.Gln324His and affecting glycosylase activity, to increase colorectal cancer risk (ORinteraction = 1.36)." (PMID 27588484, 2016). "OGG1 directly interacts with XRCC1, and the OGG1 rs1052134 showed epistasis with two XRCC1 SNPs in colorectal cancer risk." (PMID 27588484, 2016). "In a complementary way, it has been shown that patients with colorectal cancer have low levels of OGG1 expression in tumor tissue compared with normal tissue." (PMID 25268610, 2014). "In summary, our data show that patients with colorectal cancer present expression changes in several BER genes, suggesting a role for APE1, XRCC1, PARP1 and OGG1 and APE1 polymorphism in colorectal carcinogenesis." (PMID 25268610, 2014). "OGG1 Ser326Cys, APEX1 Asp148Glu and XRCC1 Arg399Gln have also been linked to a risk of colorectal cancer." (PMID 18823566, 2008). "The present retrospective cohort study aimed at investigating whether MLH1,APEX1,MUTYH,OGG1,NUDT1,XRCC5, XPA, and ERCC2 single nucleotide polymorphisms (SNPs) are associated with colorectal cancer (CRC) in Chinese population with Lynch syndrome." (PMID 29664240, 2018). "The MUTYH and OGG1 genes present downregulation in the more advanced stages of colorectal cancer." (PMID 29257843, 2017). "Previous reports have suggested that OGG1 Ser326Cys is associated with colorectal cancer in Caucasians, but not among Koreans." (PMID 18823566, 2008). "Although the Ser326Cys polymorphism of 8-oxoguanine DNA glycosylase (hOGG1) is consistently associated with a range of cancers, there is no consensus regarding this polymorphism and colorectal cancer risk." (PMID 17827862, 2007). "An in vitro study in human colorectal carcinoma cells showed that when cells were treated with methylmethane sulfonate (a DNA-alkylating agent), OGG1 mRNA levels increased significantly, and the increased levels of OGG1 expression were correlated with increase in enzyme activity." (PMID 16759981, 2006). "However, if a person already is at enhanced risk for colorectal cancer due to deficiencies in DNA mismatch repair causing Lynch syndrome, this risk was not further elevated by low penetrance alleles such as the OGG1 Cys326 variant." (PMID 34199885, 2021).
colorectal cancer (continued). "Since early-onset colorectal cancer (CRC) is a characteristic of MAP and might be caused by the inactivation of another 8-hydroxyguanine repair gene, OGG1, we investigated whether germline MUTYH and OGG1 mutations are involved in early-onset CRC in Japanese patients." (PMID 24799981, 2014). "Interestingly, recent reports suggest that PD-L1 expression is negatively correlated with BER gene expression, including OGG1 and APE1, and that anti-PD-1 therapy in combination with ionising radiation is stimulated by PARPi in colorectal cancer models." (PMID 32648895, 2020). "Furthermore, our data show that patients with colorectal cancer present expression changes in several BER genes, suggesting a role for APE1, XRCC1, PARP1 and OGG1 in colorectal carcinogenesis." (PMID 25268610, 2014).
pulmonary fibrosis (17 papers, 2015 to 2025). Chronic progressive interstitial lung disorder characterized by the replacement of the lung tissue by connective tissue, leading to progressive dyspnea, respiratory failure, or right heart failure. "This was further validated by the finding that Ogg1 deficiency attenuated bleomycin-induced pulmonary fibrosis by constructing Ogg1−/− mice." (PMID 40867876, 2025). "Next, to further confirm the molecular regulation of OGG1/PINK1 during pulmonary fibrosis, the loss- and gain-of function experiments were conducted in vitro." (PMID 38822247, 2024). "In the present study, we made a further exploration on the regulatory mechanism of OGG1 impacting the progression of pulmonary fibrosis, which was closely associated with macrophages polarization and mitophagy." (PMID 38822247, 2024). "The base excision repair enzyme, 8-oxoguanine DNA glycosylase 1 (OGG1), plays a critical role in repair of mtDNA oxidative damage, OGG1 deficiency or inactivation predisposes to pulmonary fibrosis." (PMID 29459894, 2018). "In addition, they demonstrated that OGG1 deficiency relieved pulmonary fibrosis and decreased the expression of Smad7 and phosphorylation of SMAD2/3 in bleomycin‐treated mice." (PMID 36788635, 2023). "Researchers ascertained that OGG1 interacted with the TGF-β/Smad axis to promote the progression of pulmonary fibrosis in a BLM (bleomycin)-induced mouse model of pulmonary fibrosis." (PMID 40867876, 2025). "Conversely, in the bleomycin-induced pulmonary fibrosis model, OGG1 demonstrated a pro-inflammatory function, a property that can be explained by the prevalence of α isoforms." (PMID 40867876, 2025). "OGG1 inhibitors also mitigate bleomycin-induced pulmonary fibrosis and bacterial lung infections in mice, by reducing inflammatory responses." (PMID 39837827, 2025). "The protective role of OGG1 inhibition against pulmonary fibrosis is archived partly via activating PINK1/Parkin mitophagy and retarding M2 macrophage polarization." (PMID 38822247, 2024). "In agreement with previous studies, our findings revealed that OGG1 expression was elevated following BLM-induced pulmonary fibrosis, accompanied with elevated M2 macrophages." (PMID 38822247, 2024). "In summary, this study provides substantial evidence indicating the involvement of OGG1 during pulmonary fibrosis and alleviation of pulmonary fibrosis by OGG1 inhibition." (PMID 38822247, 2024). "Previous studies have highlighted the protective role of OGG1 inhibition against pulmonary fibrosis in animal model; however, the specific mechanism of action for its regulatory role has been not clarified yet." (PMID 38822247, 2024). "8-Oxoguanine DNA glycosylase (OGG1), a well-known DNA repair enzyme, has been demonstrated to promote lung fibrosis, while the specific regulatory mechanism of OGG1 during pulmonary fibrosis remains unclarified." (PMID 38822247, 2024). "OGG1 is also demonstrated to promote lung fibrosis via regulating TGFβ/SMAD signaling and activating fibroblasts." (PMID 38822247, 2024). "Our findings shed novel insights on the molecular mechanism by which OGG1 influenced the development of pulmonary fibrosis." (PMID 38822247, 2024). "Taken together, OGG1/PINK1/mitophagy axis in fibroblasts played a crucial role in regulating pulmonary fibrosis and the relevant macrophage polarization." (PMID 38822247, 2024). "In this study we show Ogg1-targeting siRNA mitigates bleomycin-induced pulmonary fibrosis in male mice, highlighting OGG1 as a tractable target in lung fibrosis." (PMID 36746968, 2023). "We next investigated TH5487-mediated Ogg1 inhibition in vivo using a murine model of pulmonary fibrosis." (PMID 36746968, 2023).
pulmonary fibrosis (continued). "In Ogg1−/− mice, bleomycin-induced pulmonary fibrosis was relieved, and their findings indicated that OGG1 is a potential molecular target for treating pulmonary fibrosis." (PMID 36421478, 2022). "We reason that the OGG1/ACO-2/SIRT3/mtDNA axis is important in regulating complex cell signaling that promotes pulmonary fibrosis as well as other degenerative disease of the lungs and tumor development." (PMID 26370974, 2015). "Furthermore, the use of TH5487, a pharmacological inhibitor of OGG1, in the middle stage of lung fibrosis, has been shown to alleviate BLM-induced lung fibrosis in murine models." (PMID 40867876, 2025). "The study’s findings indicate that OGG1 may exert variable effects on distinct etiologies of pulmonary fibrosis, with its role being particularly pronounced in the mitigation of particulate matter-induced pulmonary fibrosis." (PMID 40867876, 2025). "Therefore, OGG1 appears to be a promising clinical target with therapeutic potential for pulmonary fibrosis." (PMID 38822247, 2024). "Therefore, in the present study, we focused on the regulatory mechanism of OGG1 in pulmonary fibrosis using both in vivo and in vitro approaches." (PMID 38822247, 2024). "In BLM-induced pulmonary fibrosis, OGG1 was upregulated while PINK1/Parkin was downregulated." (PMID 38822247, 2024). "We set up a bleomycin (BLM)-induced mouse pulmonary fibrosis model, and demonstrated that TH5487, the small molecule OGG1 inhibitor, could attenuate pulmonary fibrosis, activate PINK1/Parkin mitophagy and reduce M2 macrophage polarization." (PMID 38822247, 2024). "Wherever, the relief caused by TH5187 treatment was partly abolished by additional treatment with Mdivi-1, indicating that inhibition of OGG1 might relieve pulmonary fibrosis partly through activating mitophagy." (PMID 38822247, 2024). "Therefore, OGG1 has been considered as a critical mediator in the pathogenesis of pulmonary fibrosis." (PMID 38822247, 2024). "Lastly, OGG1 is a mediator of pulmonary fibrosis sparked by bleomycin; the underlying mechanism is alveolar epithelial–mesenchymal transition (EMT) and can be inhibited by small-molecule OGG1 inhibitor TH5487 or enhanced by OGG1 overexpression." (PMID 38201575, 2023). "However, substantial evidence also convincingly confirms that OGG1 led to a reduction in pulmonary fibrosis development." (PMID 36421478, 2022). "OGG1 is essential for the remission of pulmonary fibrosis in mice exposed to PM2.5 or crocidolite." (PMID 36421478, 2022). "The degree of OGG1 restoration varies in different lung injury settings; maybe its tissue repair is excessive in bleomycin-induced pulmonary fibrosis." (PMID 36421478, 2022). "There are inconsistent effects in both OGG1 and OGG1 inhibitors in pulmonary fibrosis." (PMID 36421478, 2022). "Consistently, in the present study, we found that OGG1 could negatively regulate PINK1/Parkin expression during pulmonary fibrosis both in vivo and in vitro, providing evidence that OGG1/PINK1/mitophagy axis acted as a critical mediator against pulmonary fibrosis through." (PMID 38822247, 2024). "Consistently, the western blot assay revealed that protein expression of OGG1 was significantly increased in BLM group, while the protein expression of PINK1 and Parkin was significantly decreased, suggesting that OGG1/PINK1 mitophagy might be involved in the progression of pulmonary fibrosis." (PMID 38822247, 2024). "Meanwhile, TH5487 exerted an inhibitory effect on BLM-elevated CD206 expression, which was partly restricted by Mdivi-1, indicating that inhibition of OGG1 could retard M2 macrophage polarization following pulmonary fibrosis partly through activating mitophagy." (PMID 38822247, 2024). "Furthermore, overexpression of SIRT3 restored the levels and activity of OGG1 and prevented mtDNA damage to rescue the transformation of lung fibroblasts to myofibroblasts, implicating that OGG1 is beneficial in attenuating the development of pulmonary fibrosis." (PMID 36421478, 2022).